MTOR (mechanistic target of rapamycin kinase)
Diseases named in the same sentence as MTOR in open-access papers (continued):
Sharing a sentence is not in itself a finding about the gene and the disease.
prostate carcinoma (continued). "Comforting our data, a relationship between Tau and the PI3K/Akt pathway has been previously proposed since the down-regulation of Tau in Docetaxel-resistant prostate cancer cells rescued drug resistance by inhibiting the PI3K/Akt/mTOR signaling pathway." (PMID 34830972, 2021). "Another widely studied driver of prostate cancer is the dysregulation of the PTEN/PI3K/AKT/mTOR signaling that is frequently target of epigenetic and post-translational modifications as well as genetic alterations in prostate cancer." (PMID 33572160, 2021). "Akt/mTOR signaling has been found to promote cancer cell proliferation and is known to be activated in prostate cancer cells." (PMID 34831037, 2021). "PRRT3-AS1 controls the mTOR signaling pathway to promote the invasion and metastasis and inhibits the autophagy and apoptosis of prostate cancer cells." (PMID 34604045, 2021). "Some studies have suggested that MYC cooperates with the dysregulation of the PI3K/AKT/mTOR pathway to promote PCa cell survival and promote oncogenic signaling in prostate cancer." (PMID 39697534, 2021). "For instance, paradigmatic examples of affected cancer pathways emerging from our analyses are Ras and Wnt in colon cancer and the PI3K and mTor pathways in breast and prostate cancers." (PMID 34115745, 2021). "SREBF1 was involved in fatty acid metabolism, and expression of SREBF1 mediated by AR/mTOR complex accelerated metabolism of fatty acid, to meet the demand for prostate cancer cell growth." (PMID 34116604, 2021). "Correspondingly, silencing SIRT6 suppressed the downstream molecules of mTOR pathway in both prostate cancer cell lines and in vivo tissue samples." (PMID 33995674, 2021). "According to the results of the network pharmacology, the potential mechanism of XHP to treat prostate cancer was via PI3K/Akt/mTOR signaling pathway." (PMID 35342388, 2021). "Everolimus, an mTOR inhibitor, has been assessed in mice, resulting in an inhibition of prostate cancer growth." (PMID 34615934, 2021). "An elevated level of cholesterol esters appears with mutations in the kinase genes of phosphatase and the tensin homolog (PTEN)/PI3K3/mTOR) pathway, which are correlated with a higher stage and Gleason score in prostate cancer cells." (PMID 33401726, 2021). "In prostate cancer stem cells, it represses mTOR, which is accompanied by an increase in the expression of ATG proteins, including ATG5, ATG7, ATG12 and Beclin1." (PMID 34575981, 2021). "Recent in vitro data have also revealed that mTOR can directly interact with AR in the nucleus of prostate cancer cells to promote metabolic rewiring, and high levels of nuclear mTOR correlate with poor prognosis in patients with prostate cancer." (PMID 32630372, 2020). "Recent studies in prostate cancer cells have been shown that CSCs with EMT are resistant to radiation therapy through the PI3K/AKT/mTOR pathway." (PMID 32376896, 2020). "Mechanistically, we showed that endothelial cells-derived FGF2 mediated ERG expression and Akt/mTOR activation in prostate cancer cells." (PMID 33425737, 2020). "Hsa-mir-99a-5p enhanced the radiation sensitivity of non-small cell lung cancer by targeting mTOR, and inhibition of the glucocorticoid receptor resulted in an enhanced hsa-mir-99a-5p-mediated radiation response in stem-like cells from human prostate cancers." (PMID 33033230, 2020). "Mechanistically, basic fibroblast growth factor (FGF2) secreted by endothelial cells leads to the upregulation of ETS related gene (ERG) expression and activation of the Akt/mTOR signaling pathway in prostate cancer cells to promote docetaxel resistance." (PMID 33425737, 2020). "Specifically, we demonstrated that FGF2 secreted from endothelial cells can upregulate ERG expression in prostate cancer, which then activates the Akt/mTOR signaling pathway and promote docetaxel resistance of prostate cancer subsequently." (PMID 33425737, 2020).
prostate carcinoma (continued). "The activation of the Akt/mTOR signaling pathway promotes the docetaxel resistance of prostate cancer cells ultimately." (PMID 33425737, 2020). "Although activation of the Akt-dependent mTOR pathway is usually present in prostate cancer, it has been reported that mTOR activation is also dependent on kinases other than Akt." (PMID 32630532, 2020). "For instance in prostate cancer, where the Pi3k/Akt/mTOR signaling pathway plays a pivotal role in DXT resistance, quercetin treatment decreased both Akt and p-Akt protein expression and induced apoptosis." (PMID 32492961, 2020). "It was possible that antitumor effect of isorhamnetin on androgen-insensitive prostate cancer is achieved by suppressing the PI3K-Akt–mTOR pathway." (PMID 32039440, 2020). "Merr., caused cytotoxic and apoptotic effects on DU145 prostate cancer cells by inducing sub-G0/G1 cell cycle arrest and autophagic cell death through the inhibition of the PI3K/AKT/mTOR signaling pathway." (PMID 33552000, 2020). "Below we explore several potential mechanisms underpinning deregulation of the AMPK-AKT/mTOR signaling axis in prostate cancer." (PMID 32630372, 2020). "Accordingly in a prostate cancer model, osteoblasts induce mTOR signaling by releasing GAS6, and this preserves CSC dormancy." (PMID 33193295, 2020). "Inhibition of the classic PI3K/Akt/mTOR autophagy pathway can significantly reduce the level of autophagy in prostate cancer cells, and suppress homologous recombination repair." (PMID 33575215, 2020). "Increased mTOR signaling is associated with lymph node progression and increased lymphangiogenesis in advanced prostate cancer, supporting a link between mTOR activation and metastatic spread of PCa." (PMID 32656088, 2020). "A positive relationship between MDM2 inhibition and the inhibition of the phosphoinositide 3-kinase (PI3K)/mechanistic target of rapamycin (mTOR)/E-twenty six proto-oncogene 2 (ETS2) pathway was identified in PC3 prostate cancer cells." (PMID 33182828, 2020). "Fisetin can function as an inhibitor of the expression of PI3K/Akt/mTOR pathways and regulate autophagy in prostate cancer and human NSCLC cells." (PMID 33228222, 2020). "Fisetin has been found to inhibit the mTOR pathway and induce autophagy in human prostate cancer cells." (PMID 33228222, 2020). "While homozygous loss of Pten causes embryonic lethality, heterozygous deletion is viable, but prone to the development of prostate cancer due to the moderate activation of PI3K/AKT/mTOR signaling." (PMID 31685947, 2020). "CCI779 is an mTOR inhibitor; its anti-cancer activity has been demonstrated in colorectal carcinoma and prostate cancer." (PMID 33396624, 2020). "Significantly, SGK1 inhibition is reported to reduce prostate cancer cell line proliferation and invasive potential, and can synergize with the mTOR inhibitor rapamycin in vitro." (PMID 33105713, 2020). "Herein, docetaxel resistance of ERG-overexpressing prostate cancer cells was significantly reversed when Perifosine, the inhibitor of the Akt/mTOR signaling pathway was added, which was in agreement with the previous report." (PMID 33425737, 2020). "In PC3 prostate cancer cells, UA-induced autophagy was facilitated by the Akt/mTOR and Beclin-1 pathways." (PMID 33228222, 2020). "The obtained findings justify the clinical use of mTOR inhibitors in therapy in patients with cancers, including transplant recipients suffering from prostate cancer." (PMID 32604947, 2020). "The combination of everolimus, another mTOR inhibitor, and propachlor synergistically enhanced cell death by inducing autophagic cell death in prostate cancer cells." (PMID 33239065, 2020). "A combinatory treatment of quercetin with DTX was especially effective against DTX-resistant prostate cancer cells through the Pi3k/Akt/mTOR signaling pathway inhibition." (PMID 32492961, 2020).
prostate carcinoma (continued). "On the other hand, piperine treatment inhibited AKT phosphorylation and mTOR pathway in DU145 prostate cancer cell line preventing cell migration." (PMID 32669593, 2020). "Recent advances in radiotherapy also indicate that triggering of the PI3K/AKT/mTOR pathway is closely relevant to radioresistance, which is a major challenge for current radiation treatment in prostate cancer (CaP) and other cancers." (PMID 32373608, 2020). "ERG protein activates Akt/mTOR signaling pathway contributing to docetaxel resistance in prostate cancer cells ultimately." (PMID 33425737, 2020). "The aims of this investigation include identification of the potential benefit of the PIM-PI3K/mTOR co-targeted inhibition approach by analysis of publicly available data on prostate cancer patient populations." (PMID 32873828, 2020). "There was an obvious decrease in β-catenin, p-AKT, and p-mTOR in cir-ITCH-overexpressed prostate cancer cells, and in both androgen receptor-positive LNCaP cells and androgen receptor-negative PC-3 cells." (PMID 32904490, 2020). "EpCAM is also reported to regulate the AKT/mTOR signaling and, in turn, to be involved in prostate cancer radioresistance." (PMID 33490064, 2020). "Collectively, these findings suggested that ERG enhances docetaxel resistance via the Akt/mTOR signaling pathway in prostate cancer cells." (PMID 33425737, 2020). "Studies have shown that activation of the PI3K/AKT signaling pathway can promote prostate cancer cell invasion and the PI3K/AKT/mTOR pathway is associated with advanced prostate cancer and bone metastasis." (PMID 32904490, 2020). "The activation of the Akt/mTOR pathway contributed to the docetaxel resistance of prostate cancer, which was corroborated in previous studies." (PMID 33425737, 2020). "miR-410-3p targets and downregulates the expression of PTEN in prostate cancer leading to activation of AKT/mTOR pathways and promotion of cancer progression." (PMID 31165412, 2019). "We suggest that AICAR induces apoptosis and inhibits migration of prostate cancer cells through an AMPK/mTOR-dependent pathway." (PMID 30987073, 2019). "On the other hand, it has been demonstrated that PI3K/Akt/mTOR inhibitors enhance radiosensitivity of radioresistant prostate cancer cells in part by downregulating proteins involved in HR (such as Rad51) and NHEJ (such as Ku70/Ku80)." (PMID 31780937, 2019). "Fisetin was found to be an inhibitor of PI3K/Akt/ mTOR pathways and an inducer of autophagia in prostate cancer cell lines." (PMID 31064104, 2019). "In a study of prostate cancer cell lines, mTOR inhibitors enhanced GAS5 transcript levels in androgen-sensitive but not in androgen-independent cell lines, which exhibit especially low levels of endogenous GAS5 lncRNA." (PMID 31533355, 2019). "Several studies have established that autophagy is associated with drug resistance in prostate cancer cells to ADT and inhibitors of PI3K/Akt/mTOR signaling." (PMID 30935141, 2019). "In breast and prostate cancer cell lines, Curcumin inhibits Akt and mTOR function even in the presence of EGF, a ligand of the EGF receptor." (PMID 30766532, 2019). "The integrins α7 and β3 in renal cell carcinoma, and α5 and β4 in prostate cancer cells have been shown to be translocated when mTOR has been blocked." (PMID 31167517, 2019). "Other target genes such as CDC25A, mTOR were not affected, although miR-100 was reported to cooperate with other factors to down-regulate mTOR pathway in prostate cancer." (PMID 31293973, 2019). "In prostate cancer cells, the ribosomal protein S6, a downstream target of p70S6K and the Akt/mTOR signaling cascade was identified as a potential target of palmatine." (PMID 31027283, 2019). "miR-410-3p triggers prostate cancer progression through regulation of PTEN/AKT/mTOR signaling pathway." (PMID 31262971, 2019).
prostate carcinoma (continued). "Hsieh and colleagues demonstrated that mTOR enhances the migration and invasion of prostate cancer cells by affecting certain genes that are controlled by translation, and developed an ATP site inhibitor of mTOR that prevents prostate cancer metastasis." (PMID 31671902, 2019). "The mechanistic target of rapamycin (mTOR) is elevated in prostate cancer, making this protein attractive for tumor treatment." (PMID 31010254, 2019). "mTOR signaling regulates translation of mRNA involved in the biology of prostate cancer proliferation, metabolism, and invasion." (PMID 30842412, 2019). "Over-activation of phosphatidylinositol 3-kinase (PI3K)-AKT-mammalian target of rapamycin (mTOR) signaling pathway is one of important mechanisms to promote castration resistant prostate cancer, the final stage of prostate cancer (PCa)." (PMID 31092266, 2019). "Quercetin was also documented to impede tumor proliferation and angiogenesis by targeting the VEGF receptor-2 (VEGF-R2) and Akt/mTOR/P70S6K signaling pathway in a mouse prostate cancer xenograft model." (PMID 31064104, 2019). "mTOR is the downstream gene that is positively regulated by AR in prostate cancer cells, and the repression of the mTOR signal also exhibits a compensatory increase in AR function." (PMID 29713287, 2018). "REDD1 has been identified as a negative regulator of mTOR and a new molecular target of metformin in prostate cancer cells." (PMID 29416762, 2018). "Prostate cancer radio-resistance is associated with EMT and enhanced CSC phenotypes via activation of the PI3K/Akt/mTOR signalling cascade." (PMID 29385093, 2018). "Mutations in SPOP lead to genomics instability and are identified as driver events resulting in tumorigenesis of prostate carcinoma via coordination with PI3K/mTOR and AR (Androgen Receptor) pathway in mouse." (PMID 29986747, 2018). "CXCL8 enhanced resistance to anoikis in colorectal cancer cells, promoted castration-resistant through PI3K/AKT/mTOR pathway and regulating cyclin D1 in prostate cancer cells." (PMID 30723697, 2018). "Shikonin potently suppressed PC-3 and DU145 cell metastasis in a dose-dependent manner (0.5–2 μΜ) and inhibited the migration and invasion of the two aggressive prostate cancer cell lines by reducing MMP-2/-9 expression via AKT/mTOR and ROS/ERK1/2 pathways." (PMID 29495626, 2018). "Inhibitory effects of EGCG have focused on the expression of EGFR, HER-2, and androgen receptors, leading to decreased expression of PI3K/AKT/mTOR signaling in colon and prostate cancer cells." (PMID 29588626, 2018). "DHA and EPA also reduced the growth of LNCaP prostate cancer cells via suppression of AKT/mTOR signaling." (PMID 30213082, 2018). "This drug stimulates autophagosome formation by downregulating the AKT/mTOR pathway and inhibits the autophagic flux by increasing lysosomal pH and affecting autolysosomal maturation in LNCaP prostate carcinoma cells." (PMID 29500364, 2018). "WIN-55 was also reported to inhibit differentiation of prostate cancer cells via down regulating the PI3K/Akt/mTOR signaling pathway." (PMID 29792186, 2018). "DHA-induced apoptosis mediated ROS-Akt-mammalian target of rapamycin (mTOR) signaling in prostate cancer cells." (PMID 30400136, 2018). "Of further interest, GAS5 lncRNA has been found to supress the AKT/mTOR signaling pathway in prostate cancer cells." (PMID 30087896, 2018). "Recent evidence has supported that inhibition of mTOR contributed to cell cycle arrest in prostate cancer radioresistant cells." (PMID 30518405, 2018). "Oleanolic acid also suppresses the PI3K/Akt/mTOR signaling pathway to inhibit cell survival and proliferation of prostate cancer cells." (PMID 29636693, 2018). "The phosphoinositide 3-kinase (PI3K)/Akt/mTOR signaling pathway is always constitutively activated in advanced stages of prostate cancer." (PMID 29228561, 2017).
prostate carcinoma (continued). "Previous research conducted in prostate cancer showed that AR positively regulated mTOR activity and compensatory increase of AR function due to a repressed mTOR signal is advantageous for tumor cell survival." (PMID 28060723, 2017). "In a prostate cancer study, abnormal CAPN2 expression was associated with cell metastasis and proliferation by activating AKT/mTOR signaling." (PMID 29228653, 2017). "Data from the in vitro study further suggested that the efficacy of DR17 treatment resulted, in part, from the targeting of multiple prostate cancer relevant signaling pathways including PI3K/AKT/mTOR and HSP90/HSP70/AR." (PMID 28350865, 2017). "Another study investigated the use of mTOR inhibitor RAD001 for radiosensitising prostate cancer cell lines DU145 and PC3." (PMID 28320471, 2017). "Unambiguously, the VEGFR2 was shown to regulate protein kinase B (Akt)/mammalian target of rapamycin (mTOR)/ribosomal protein S6 kinase beta-1 (P70S6K) signalling pathway in PC-3 prostate cancer cell line." (PMID 28143503, 2017). "The PI3K/AKT/mTOR and the Androgen Receptor signalling pathways are important drivers of prostate cancer growth and progression." (PMID 28915623, 2017). "GPRC6A edited PC-3 cells exhibited an attenuated response to L-Arg, osteocalcin and testosterone stimulation of ERK, Akt, and mTOR phosphorylation compared to controls, pathways involved in advanced prostate cancer and emergence of hormone-refractory disease." (PMID 28659174, 2017). "The current study shows that by activating GPRC6A, signaling via ERK, AKT, and mTOR is increased in prostate cancer cells." (PMID 28659174, 2017). "Cross-communication has recently been observed in a prostate cancer cell line in a manner that enhanced histone H3 and H4 acetylation triggered elevated Akt-mTOR activity, particularly seen with pRictor." (PMID 29299126, 2017). "Several studies demonstrated that autophagy was induced by VPA treatment through the downregulation of the AKT/mTOR pathway in prostate cancer." (PMID 28498322, 2017). "We previously reported that BITC induces protective autophagy in human prostate cancer cells via the inhibition of mTOR signaling." (PMID 28423628, 2017). "mir-99a and mir-99b inhibit proliferation of c-Src-transformed cells and prostate cancer cells by targeting mTOR and were identified as novel targets in some important biological process, such as the TGF-β-induced epithelial to mesenchymal transition." (PMID 28335741, 2017). "Inhibition of mTOR has been shown to result in expansion of immunosuppressive regulatory T cells (Tregs) in patients with metastatic renal cell carcinoma or prostate cancer." (PMID 29070044, 2017). "Expression of miR-96 in prostate cancer cells to moderate levels induced autophagy through direct suppression of mTOR." (PMID 28459042, 2017). "At the molecular level DR17 targeted simultaneously several molecular signaling axes important in prostate cancer including androgen receptor, mTOR, and PI3K/AKT." (PMID 28350865, 2017). "We have recently discovered a new molecular mechanism of prostate cancer docetaxel chemoresistance mediated by the mammalian target of rapamycin (mTOR)/sphingosine-kinase-1 (SK1) pathway." (PMID 28615679, 2017). "Paeonol possessed an anti-proliferation effect on human prostate cancer cells and significantly inhibited phosphorylation status of Akt and mTOR." (PMID 29354055, 2017). "In a previous study, we revealed that RAD001 sensitizes PC3 and DU145 prostate cancer cells and tumours to docetaxel therapy through downregulation of mTOR/SK1 pathway." (PMID 28615679, 2017). "The aim of this study was to determine the importance of the PI3K/AKT/mTOR pathway in human prostate cancer." (PMID 28915623, 2017).